MCL1 (MCL1 apoptosis regulator, BCL2 family member)
Diseases named in the same sentence as MCL1 in open-access papers (continued):
Sharing a sentence is not in itself a finding about the gene and the disease.
melanoma (continued). "Thus, dependency on MCL1 when the ERK1/2 pathway was inhibited was observed in melanoma cell lines and primary patient-derived melanoma cells." (PMID 31727888, 2019). "Similarly demethylzeylasteral and 9, 11-dehydroergosterol peroxide induce apoptosis in melanoma cells by down regulating MCL-1." (PMID 31191820, 2019). "Consequently, E7107 selectively induces apoptosis in BCL2A1-dependent melanoma cells and MCL1-dependent NSCLC cells." (PMID 30635584, 2019). "Thus, MCL1 is critical in restraining pro-apoptotic BH3-only proteins induced by ERK1/2 inhibition in melanoma." (PMID 31727888, 2019). "Consequently the MCL1:BCL-XL ratio was substantially biased towards MCL1 in melanoma; the median ratio was 5–6 in melanoma vs. ~1 in CRC and pancreatic tumour cells, and ~2 in NSCLC." (PMID 31727888, 2019). "While MCL1 expression in the CCLE data set was broadly similar in CRC and melanoma cells, and slightly higher in NSCLC and pancreatic, levels of BCL2L1 (encoding BCL-XL) were strikingly lower in melanoma relative to the other lineages." (PMID 31727888, 2019). "Consequently, the MCL1:BCL-XL mRNA ratio, encoding the major pro-survival proteins in solid tumours, was two- to four-fold higher in melanoma than in the other lineages." (PMID 31727888, 2019). "However, single drug BH3 mimetic therapy in melanoma has limited effectiveness due to escape by the anti-apoptotic protein MCL-1 and/or survival of melanoma-initiating cells (MICs)." (PMID 30185782, 2018). "It is known that miR-339-3p functions as a suppressor in melanoma by targeting the oncogene MCL1." (PMID 30332417, 2018). "cPARP is increased in melanoma cells in response to the drug combination, with concomitant decrease in levels of the anti-apoptotic Bcl-2 family member, MCL-1, showing that combined leflunomide and selumetinib treatment increases apoptosis in melanoma cells compared with individual drug treatment." (PMID 29423085, 2018). "This further supports that an MCL-1/BCL-2 co-targeting strategy could be beneficial for melanoma patients, especially those relapsed from other treatments." (PMID 27086916, 2017). "Conversely, knocking down of MCL1 in melanoma cells increased the ubiquitinated CDK2." (PMID 29072681, 2017). "In order to reveal whether downregulation of MCL1 is involved in effects induced by demethylzeylasteral, we dosed MCL1- and empty vector-overexpressed melanoma cells with 5 μM demethylzeylasteral, DMSO and empty vector were used as control." (PMID 29072681, 2017). "Indeed, ERK-dependent up-regulation of MCL1 has been proposed to account for the resistance of some melanoma cells to ER stress." (PMID 28931068, 2017). "MCL-1 (BCL-2 family anti-apoptotic protein) is responsible for melanoma's resistance to therapy." (PMID 27086916, 2017). "Therefore, the anti-apoptotic protein MCL-1 is a potential treatment target for a broad range of melanomas." (PMID 27086916, 2017). "Mcl-1 accumulation was also found in melanoma cell line A375 after 24-h treatment with MG-132." (PMID 28281027, 2017). "While mRNA profiling suggests that Bfl-1 confers apoptotic resistance in SK-MEL-5 and LOX-IMVI melanomas, our combinatorial antagonism of pro-survival homologs indicates that Mcl-1 plays a more critical role and further discriminates between sensitive LOX-IMVI and resistant SK-MEL-5." (PMID 27805565, 2016). "Overall, these data demonstrate that although we cannot detect lowering of Mcl-1 by 2 mM of 2-DG or 40 μM of FF alone in the melanoma cell line studied, combining the two, results in marked reduction of this critical anti-apoptotic protein which leads, at least in part, to cell death." (PMID 27183907, 2016). "Importantly, both miR-32 replacement therapy and the MCL-1-specific antagonist sabutoclax demonstrated single-agent efficacy, and acted synergistically in combination with vemurafenib in preclinical melanoma models." (PMID 27846237, 2016).
melanoma (continued). "MCL-1 protein was found to be expressed at low levels in human primary melanocytes; however, it was expressed at high levels (over 20-fold) in patient-derived melanoma cell lines (primary tumor and stage II/III metastatic melanoma)." (PMID 27846237, 2016). "The combination also increased the NOXA/MCL-1 ratio in all the melanoma patient samples tested." (PMID 27829238, 2016). "Searching for other cell-autonomous differences which might account for lack of PN-induced senescence in DMBC12 population, we examined basal MCL-1 level in untreated melanoma cells." (PMID 26824319, 2016). "Stimulation with IGF-1 for 24 h significantly increased the expression levels of STAT3-targeted genes, including survivin, BCL-XL, and MCL-1, while IT pretreatment for 2 h markedly decreased IGF-1-induced survivin, BCL-XL, and MCL-1 expression in human melanoma A375S and A2058 cells." (PMID 27323414, 2016). "Given the crosstalk demonstrated by our data and the findings reported in the literature, we reasoned that co-targeting BRAFV600E and the MCL-1 pathway might represent an effective combination anti-melanoma strategy." (PMID 27846237, 2016). "MCL-1 was upregulated in human malignant melanoma as compared to nevi." (PMID 27846237, 2016). "An increase in Annexin V-positive cells and apoptotic/necrotic cells was obtained when melanoma population with silenced expression of MCL-1 was exposed to serum-containing medium when compared to the same population concomitantly exposed to fresh EGF(+)bFGF(+) medium." (PMID 26035829, 2015). "Moreover, thapsigargin which increase intracellular calcium concentration via SERCA inhibition induces Mcl-1 expression in melanoma." (PMID 25627260, 2015). "Moreover, we have revealed that Mcl-1 has a major role in regulation of EGb761-induced apoptosis in melanoma cells." (PMID 25860257, 2015). "Since Mcl-1 was differentially regulated by EGb761 in Mel-RM and Mel-AT cells with different sensitivity to EGb761-inudced apoptosis, we further study the role of Mcl-1 in regulation of apoptosis triggered by the compound in melanoma cells by knocking down of Mcl-1 using siRNA." (PMID 25860257, 2015). "Mcl-1 is known to be critical for survival of melanoma cells under various stress conditions." (PMID 25860257, 2015). "Furthermore, stability of anti-apoptotic protein Mcl-1 in melanoma cells is regulated by ERK1/2, and enhanced expression of this protein in melanoma cells has demonstrated resistance against BRAF inhibitor-induced apoptosis." (PMID 26299806, 2015). "MCL-1 dependence seems to be especially important in melanoma populations with high MITF level and activity, whereas in populations in which MITF is expressed at low levels, BCL-XL may be sequentially involved after MCL-1 expression is reduced." (PMID 26035829, 2015). "When results of qRT-PCR, immunoblotting and functional assay are concerned, MCL-1 may be considered as an important pro-survival contributor to the immediate response of melanoma cells to serum." (PMID 26035829, 2015). "Indeed, inhibition of Mcl-1 by siRNA enhanced apoptosis induced by EGb761 in both sensitive and resistant melanoma cells." (PMID 25860257, 2015). "This provided initial evidence that overexpression of Mcl-1 might be responsible for acquired resistance to BRAF inhibitors in melanoma cells." (PMID 26497853, 2015). "MCL1 was also considered an actionable mutation since patients were referred to a clinical trial (NCT01303341) of riluzole and sorafenib in patients with advanced solid tumors and melanoma." (PMID 26082439, 2015). "Consistently in all four melanoma populations, MCL-1 protein level increased peaking after 2 h." (PMID 26035829, 2015). "Moreover, our results suggest that combination of BRAF inhibitors with Mcl-1 targeted therapies were successful in overcoming acquired resistance in melanoma in vitro and in vivo." (PMID 26497853, 2015).
melanoma (continued). "In contrast to a study on the established melanoma cell lines, we have demonstrated that MCL-1 inhibition by specific siRNA did not cause significant cell death in patient-derived melanoma populations." (PMID 26035829, 2015). "The expression of Mcl-1 is also known to increase in melanoma with disease progression." (PMID 25860257, 2015). "Moreover, we show that the anti-apoptotic Bcl-2 family protein Mcl-1 plays an important role in regulation of sensitivity of melanoma cells to apoptosis induced by EGb761." (PMID 25860257, 2015). "In support of this, knockdown of Mcl-1 induces, albeit moderately, apoptosis in melanoma cells." (PMID 25365078, 2014). "Nevertheless, the pathway also plays a major role in upregulation of Mcl-1 in melanoma cells." (PMID 25365078, 2014). "Taken together, these results suggest that targeting of Mcl-1 by Maritoclax may represent a new therapeutic strategy for melanoma treatment that warrants further investigation as a single therapy or in combination with other agents such as Bcl-2 inhibitors." (PMID 24223823, 2013). "Moreover, upregulation of Mcl-1 was critical for protection of melanoma cells against endoplasmic reticulum (ER) stress-induced apoptosis and survival of melanoma cells treated with the proteasome inhibitor Bortezomib." (PMID 24367627, 2013). "Obatoclax, but not ABT-737, was also found to be a strong inducer of autophagy, suggesting Mcl-1 plays a regulatory role in autophagy and which may have contributed to the increased sensitivity of melanoma to Obatoclax." (PMID 24367627, 2013). "Since melanoma cells are dependent on Mcl-1 for survival and Maritoclax is a selective inhibitor of Mcl-1, we investigated the effects of Maritoclax on Mcl-1 expression." (PMID 24223823, 2013). "Because the over expression of Mcl-1 is frequently observed in melanoma, specifically targeting of Mcl-1 may overcome the resistance of ABT-737." (PMID 24223823, 2013). "Induction of melanoma cell death by HDAC inhibitors or blockade of the RAF/MEK/ERK pathway is associated with the up-regulation of Bim and the downregulation of Mcl-1.10, 19, 21 We have also shown previously that the combination of SAHA and PLX4720 further upregulates BimEL." (PMID 23744355, 2013). "In contrast, melanoma cells were found to be dependent on the presence of specific antiapoptotic proteins: Inhibition of Mcl-1 or A1 caused significant cell death without further apoptotic stimulus." (PMID 22292048, 2012). "In this systematic screen, Mcl-1, but also A1, have been identified as potential targets whose loss led to strong cell death induction in melanoma cell lines, whereas non-malignant cells remained unaffected." (PMID 22292048, 2012). "An intrinsic sensitivity of melanoma cell lines to Mcl-1 inhibition has been observed by others." (PMID 22292048, 2012). "Inhibition of Mcl-1 effectively induced apoptosis in most melanoma cell lines." (PMID 22292048, 2012). "Although Bcl-xL was only decreased in A2058, Mcl-1 was decreased in both melanoma cell lines." (PMID 23166634, 2012). "Despite less efficient apoptosis induction compared to Mcl-1, combined targeting of Mcl-1 and A1 caused a substantial increase in cell death in the majority of melanoma cell lines tested, without inducing apoptosis in fibroblasts or keratinocytes." (PMID 22292048, 2012). "However, the combined inhibition of Mcl-1 and A1 resulted in substantial cell death induction in all melanoma cell lines with rates ranging from 60% to 80%." (PMID 22292048, 2012). "Our data argue for a cellular state in which the survival proteins Mcl-1 and A1 are required to balance such a tumor-associated stress in melanoma, and in which their loss leads to cell death without additional apoptotic stimulus." (PMID 22292048, 2012).
melanoma (continued). "Mcl-1 specific T-cell clones effectively lysed HLA-matched melanoma cells." (PMID 21304176, 2010). "A recent study demonstrated that ABT-737 induces cell death in melanoma cell lines when combined with proteasome inhibitor MG-132 The authors also perform an experiment indicating that ABT-737-dependent cell death can be enhanced by knockdown of Mcl-1." (PMID 19684859, 2009). "However, overexpression of Mcl-1, a frequent observance in melanoma, is known to confer ABT-737 resistance." (PMID 19684859, 2009). "By comparing 25 benign nevi and 65 melanoma samples (41 primary and 24 metastases), we observed a statistically significant difference in Mcl-1 score between benign nevi and primary melanoma (P<0.0001) and between primary melanoma and metastatic disease (P = 0.04)." (PMID 19684859, 2009). "Thus inactivation of Bad and Bim through MAPK phosphorylation as well as downregulation of PUMA and upregulation of Mcl-1 by MAPKs can be assumed as contributing to melanoma cell survival and chemoresistance." (PMID 19506730, 2008). "Notably, others were able to increase the potency of bortezomib using this MCL-1 knockdown approach in melanoma cells." (PMID 18941459, 2008). "Downregulation of Mcl-1 leads to sensitization of tumor cells to different treatment regimens in vitro, as shown for cholangiocarcinoma, chronic myelogenous leukemia, sarcoma and malignant melanoma." (PMID 17014711, 2006). "High expression of Bcl-2 antiapoptotic proteins, such as Bcl-2, Bcl-XL, and Mcl-1, may also contribute to melanoma progression and chemoresistance as antisense oligos against these genes can induce death of melanoma cells." (PMID 15305193, 2004). "Previously, the presented data showed that MIM1, which possesses the capacity to inhibit Mcl-1 antiapoptotic protein, may be an efficient compound able to induce apoptosis and sensitize melanoma as well as glioblastoma multiforme cells to alkylating chemotherapeutics." (PMID 40892149, 2025). "The observed potential synergistic mode of action—expressed as cytotoxic and proapoptotic activity enhancement, detected for MIM1 and MXFL—may represent a new direction for further in vitro and in vivo experiments concerning the role of the Mcl-1 protein in the treatment of melanoma." (PMID 40807447, 2025). "While we have previously shown that MCL1 inhibitors can have direct tumor killing activity in some human uveal melanoma cell lines, we did not observe any statistically significant change in the growth of B16.F10 melanoma tumors in the immunocompromised nude mice." (PMID 38459020, 2024). "Future experiments combining MCL1 inhibitors with multiple ICIs (anti-PD-1 + anti-CTLA4 or anti-PD-1 + anti-LAG3) may help identify optimal treatment strategies for melanoma, as well as many other tumors where MDSCs prevent the efficacy of conventional therapies." (PMID 38459020, 2024). "Of note, Mcl-1 upregulation in response to S63845, seen here in two melanoma lines, was completely abrogated in combinations with SCH772984, indicating that Mcl-1 upregulation may be ERK-dependent and that this counter-regulation may be overcome by the combination." (PMID 36902392, 2023). "Thus, it was suggested that melanoma cells treated with MAPK inhibitors may become particularly dependent on Mcl-1." (PMID 36902392, 2023). "Thus, we investigated if inhibition of Bcl-xL or Mcl-1 could improve the anti-melanoma effects of RU486 and VMF." (PMID 36766760, 2023). "Upregulation of Mcl-1 could attenuate the apoptosis induced by ER stress in melanoma cells." (PMID 35609325, 2022). "Importantly, functional studies showed that knockdown of BFL-1 alongside MCL-1 caused cell death in melanoma cell lines, indicating that BFL-1 may not only be up-regulated in some melanomas, but play a role in their survival." (PMID 35900226, 2022).
melanoma (continued). "Hence, we reasoned that co-inhibition of BCL2 and MCL1 in nf1/pten-mutant melanoma cells might produce an even greater synergistic antitumor effect than observed with either inhibitor given individually with sirolimus." (PMID 34331013, 2021). "Therefore, the reduction in the migratory and invasive capacity observed in melanoma cell lines when miR-1469 is overexpressed could potentially be attributed to the effects of MCL1 on these pathways." (PMID 34469478, 2021). "In agreement with this hypothesis, we detected Mcl-1 protein in C32 amelanotic melanoma cells." (PMID 31432325, 2020). "Notably, miR-146a upregulation with concomitant increased COX2, PDL1, VEGFA, CCL2, IL6, IL8 and MCL1 expression characterized the MDSCs induced in vitro by melanoma extracellular vesicles from monocytes from healthy donors, suggesting cell type-specific regulation of the miR-146a/COX2 axis." (PMID 32967672, 2020). "Therefore, Mcl-1 protein could constitute important with high priority target for melanoma treatment including advanced stages." (PMID 31432325, 2020). "Interestingly, the present study also confirms the hypothesis that Mcl-1 may be one of the key factor that influences the chemosensitivity of malignant melanoma." (PMID 31432325, 2020). "BRAF inhibition in fact induces the formation (by melanoma cells) of a fibronectin-derived protective niche that activates signaling from α5β1 integrin/PI3K/AKT leading to an increase in the expression of the pro-survival myeloid cell leukemia 1 (MCL1) protein that mediates therapeutic escape." (PMID 32466585, 2020). "Therefore, the antiapoptotic protein Mcl-1 could be considered as a potential target for malignant melanoma treatment." (PMID 31432325, 2020). "Hence, in 3D cultures, BH3-mimetic combinations targeting MCL-1 plus BCL-XL were most effective at killing melanoma cells, consistent with our 2D culture experiments, suggesting that this could be an effective targeting strategy in vivo." (PMID 31019203, 2019). "This difference could be explained by the bias towards MCL1 in melanoma." (PMID 31727888, 2019). "Thus, exploiting specific inhibition of ERK1/2 signalling and apoptotic priming in BRAF-mutant cells coupled with the pro-survival bias towards MCL1 could afford a large therapeutic window and further improve patient outcomes in melanoma." (PMID 31727888, 2019). "Consequently, the MCL1:BCL-XL protein ratio was ~5 times higher in melanoma." (PMID 31727888, 2019). "Thus combining ERK1/2 pathway inhibitors with MCL1 antagonists in melanoma could improve therapeutic index and patient outcomes." (PMID 31727888, 2019). "Indeed, the overexpression of Bcl-2, Bcl-XL, Bcl-w, and Mcl-1 in different cancers, including glioma, neuroblastoma, melanoma, squamous carcinoma, and breast, lung, and colorectal cancer cells, leads to significant increase in their migratory and invasive properties." (PMID 31921862, 2019). "Furthermore, downregulation of antiapoptotic Bcl-2 proteins (Bcl-2, Mcl-1, and Bcl-xL) was reported in melanoma cells upon treatment with different therapeutic strategies used for TRAIL sensitization, such as chemotherapeutics and inhibitors for metabolism, HDACs, and kinases." (PMID 31083589, 2019). "Hence, BCL-XL, BCL-2 and MCL-1 are all potential clinically-relevant targets in melanoma." (PMID 31019203, 2019). "Notably Mcl-1 played a major role in EGb761-induced apoptosis in melanoma cells." (PMID 30576355, 2018). "Furthermore, MCL1 promotes epithelial mesenchymal transformation and downregulation of MCL1 expression by siRNA reduced invasion of human melanoma cell lines, comparable to the anti-invasive effect described for miR-339-3p and miR-193b, both of which representing regulators of MCL1 expression." (PMID 30197759, 2018). "However, other Usp9x substrates may also add (for example, Mcl-1) or diminish (for example, Dusp4) anti-tumour activity of Usp9x inhibition and will need to be further examined in melanoma and other tumours." (PMID 28198367, 2017).